ASB8 (ankyrin repeat and SOCS box containing 8)
Description:
May be a substrate-recognition component of a SCF-like ECS (Elongin-Cullin-SOCS-box protein) E3 ubiquitin-protein ligase complex which mediates the ubiquitination and subsequent proteasomal degradation of target proteins. Inhibits IFN-beta production through the IRF3 signaling pathway by targeting TBK1 via 'Lys-48'-linked ubiquitination, leading to its proteasomal degradation.
Synonyms: PP14212; MGC5540; FLJ21255
Tractability: PROTAC: ubiquitination databases record sites on it.
Gene: Protein-coding gene on chromosome 12 (48,147,789 to 48,181,213, reverse strand). Ensembl gene ENSG00000177981.
Subcellular location: Cytoplasm
Pathways (Reactome):
Immune System: Antigen processing: Ubiquitination & Proteasome degradation
Metabolism of proteins: Neddylation
Gene Ontology:
Molecular function: protein binding
Biological process: intracellular signal transduction; protein ubiquitination
Cellular component: cytoplasm; cytosol
Genetic constraint (gnomAD): Loss-of-function variants: 15 observed, 23.01 expected, observed/expected ratio (o/e) 0.65, 90% interval 0.44 to 1. The upper end of that interval is the gene's LOEUF score, 1, which puts it in group 4 of 6, group 1 being the genes least tolerant of losing a copy. Missense variants: 294 observed, 377.19 expected, observed/expected ratio (o/e) 0.78, 90% interval 0.71 to 0.86. Synonymous variants: 124 observed, 149.62 expected, observed/expected ratio (o/e) 0.83, 90% interval 0.71 to 0.96.
Homologues: Orthologues: macaque ASB8 (100% identical), chimpanzee ASB8 (99% identical), dog ASB8 (99% identical), guinea pig ASB8 (98% identical), rat Asb8 (98% identical), mouse Asb8 (97% identical), rabbit ASB8 (94% identical), zebrafish asb8 (79% identical), tropical clawed frog asb8 (63% identical), Caenorhabditis elegans R31.2 (21% identical).
Diseases named in the same sentence as ASB8 in open-access papers:
ASB8 is named in the same sentence as 4 diseases in open-access papers, as found by Europe PMC text mining. Sharing a sentence is not in itself a finding about the gene and the disease. The quoted sentences say what the papers report.
lung carcinoma (2 papers, 2020 to 2025). "Research on ASB8 in tumors is rare, with only one study indicating its potential role in promoting lung cancer growth and proliferation." (PMID 40739091, 2025). "ASB8 (Ankyrin Repeat and SOCS Box Containing 8) has a putative role in the growth and proliferation of lung cancer, possibly as a positive regulator." (PMID 32033399, 2020).
ASB8 also shares sentences with these, for which no sentence is quoted: cancer (1 paper); lung adenocarcinoma (1); tumor (1).